MMP9 (matrix metallopeptidase 9)
Diseases named in the same sentence as MMP9 in open-access papers (continued):
Sharing a sentence is not in itself a finding about the gene and the disease.
epilepsy (continued). "The subgroup analysis based on seizure duration in patients showed that the serum MMP-9 levels at 1–3, 24, and 72 h after seizure did not exhibit significant differences between female and male patients with epilepsy when compared with the control group." (PMID 38449733, 2024). "Neuroinflammation is closely related to the occurrence of epilepsy, which also indicates that increased MMP-9 and C3AR1 content may have a synergistic effect on the occurrence of epilepsy through inflammation." (PMID 36741285, 2023). "Thus, the current work has proved that the detection of MMP9 and C3AR1 in severe SAH patients can help to predict the incidence of epilepsy and guide the prevention of epilepsy in the process of diagnosis and treatment." (PMID 36741285, 2023). "In summary, we identified the hub genes, namely, MMP9 and C3AR1, of SAH complicated with epilepsy and determined that they may work by regulating immune cell infiltration." (PMID 36741285, 2023). "Mmp9 and Timp1 were found to be overexpressed in neuronal and glial cells and are thought to be biomarkers of blood–brain barrier (BBB) dysfunction in animal models of epilepsy and clinical patients." (PMID 36104755, 2022). "It is upregulated in epilepsy; lack of Mmp-9 impoverishes, whereas excess of Mmp-9 facilitates epileptogenesis." (PMID 27505431, 2016). "In patients who developed epilepsy as a complication of acute encephalitis no discrepancies of MMP-9 levels were found between the experimental and the control group." (PMID 28104930, 2016). "However, recent research suggests that enhanced MMP-9 activity is a major factor contributing to the pathophysiology of FXS and epilepsy." (PMID 26283917, 2015). "The BDNF to pro-BDNF ratio increases in kindled WT mice, but not in MMP-9 KO mice, during the progression of epilepsy implicating MMP-9 in pro-BDNF cleavage." (PMID 26283917, 2015). "The hypothesis has been formulated that, in the context of evolving epilepsy, pathological transsynaptic activation of NMDA receptors leads to increased MMP-9 transcription via ERK1/2 and/or PI3 kinase-dependent mechanisms." (PMID 26567100, 2014). "The meta-analysis indicated that the MMP-9 levels in China (SMD = 5.15, 95% CI = 1.62–8.68, p = 0.004), Poland (SMD = 5.31, 95% CI = 2.47–8.16, p = 0.0003), and Egypt (SMD = 1.31, 95% CI = 0.91–1.71, p < 0.00001) in epilepsy patients were higher than those in the control group." (PMID 38449733, 2024). "However, direct experimental evidence linking serum MMP-9 to neurological disorders such as epilepsy is still lacking." (PMID 38449733, 2024). "Besides, we did not use age and sex as covariates for exploring the relationship between serum MMP-9 and epilepsy due to the lack of clear criteria for dividing the age group and the absence of sex classification in some studies." (PMID 38449733, 2024). "Recently, IPR-179 (Act-03), a novel MMP2/MMP9-selective inhibitor, has been developed, which has antiseizure as well as antiepileptogenic effects and attenuates seizure-induced cognitive decline, without severe side effects, in two rodent models of epilepsy." (PMID 36289737, 2022). "Alternatively, degradation of PNNs in the PC may result from the secretion of matrix metalloproteinase-9 (MMP-9) and a disintegrin-like and metalloproteinase with thrombospondin motifs (ADAMTS) from reactive astrocytes and neurones as shown in an epilepsy model." (PMID 30618629, 2018). "However, the level of MMP-9 in patients with NPSLE manifesting as epilepsy was not higher than in patients with other neuropsychiatric diseases." (PMID 28104930, 2016). "We used dizocilpine, the NMDA receptor antagonist displaying anticonvulsant activity, to block the development of PTZ-evoked epilepsy to check whether epileptogenesis inhibition had the ability to stop PTZ-kindling-dependent induction of Mmp-9 promoter demethylation and Mmp-9 expression." (PMID 27505431, 2016).
epilepsy (continued). "An increase of the MMP-9 level was found in cerebrospinal fluid of patients with bacterial meningitis who subsequently developed epileptic seizures in comparison to the patients in whom the disease was not complicated by the development of epilepsy." (PMID 28104930, 2016). "However, the serum MMP-9 levels did not significantly differ in children with epilepsy." (PMID 38449733, 2024). "Our study shows that the serum level of MMP-9 is increased in patients with epilepsy even without recent seizures, which suggests chronic BBB disruption and ECM alterations in patients with epilepsy." (PMID 36766708, 2023). "After epilepsy induction in mice, overall MMP-9 protein levels did not change in the DG; however, there was a marked increase in the number of spines expressing MMP-9 protein and in gelatinolytic activity localized to dendrites." (PMID 26283917, 2015).
lung adenocarcinoma (71 papers, 1999 to 2026). A carcinoma that arises from the lung and is characterized by the presence of malignant glandular epithelial cells. "MMP-2 and MMP-9 were identified as factors associated with the metastatic phenotype of lung adenocarcinoma cells." (PMID 34204745, 2021). "High expression of MMP9 has been associated with low survival rates in lung adenocarcinoma." (PMID 37434173, 2023). "Lung protein CYP2E1 is related to lung adenocarcinoma, and MMP9 is associated with lung neoplasms." (PMID 35259090, 2022). "High expression of MMP9 is linked to low survival rates in lung adenocarcinoma patients." (PMID 33119681, 2020). "After stratifying by tumor histology (squamous cell carcinoma vs. adenocarcinoma), tumor MMP-9 expression was associated with a poor prognosis for relapse (p = 0.003) and OS (p = 0.033) and was an independent prognostic factor for relapse (p = 0.035) of adenocarcinoma of the lung." (PMID 25888323, 2015). "The EGFR tyrosine kinase inhibitor AG1478 inhibits the migration and invasion of human lung adenocarcinoma cells via cell cycle regulation by MMP-9." (PMID 36961882, 2023). "Recently, ABL kinases were shown to be activated by co-culture of lung adenocarcinoma cells with mesenchymal stem cells (MSCs) leading to ABL-mediated MMP-9 expression, secretion, activation of MMP-9 proteolytic activity and metastasis." (PMID 34022881, 2021). "Our analysis of a cohort of lung adenocarcinoma patients demonstrated that high expression of MMP9 significantly correlated with decreased overall survival and progression-free survival." (PMID 33119681, 2020). "The MSC-induced increase in MMP9 transcription resulted in increased secretion of MMP9 protein and a corresponding increase in MMP9 gelatinase activity among a panel of lung adenocarcinoma cells." (PMID 33119681, 2020). "The downregulation of p38 MAPK and JNK was shown to result in decreased MMP-2 and MMP-9 expressions in human lung adenocarcinoma cells." (PMID 33381308, 2020). "MMP9 has an important role in metastasis of lung adenocarcinoma that was investigated in a recent study." (PMID 31191742, 2019). "Western blot results showed elevated expression of MMP-2 and MMP-9 in the lung tissues of mice with AFG1-induced lung adenocarcinoma." (PMID 28801561, 2017). "High‐level MMP9 activity is correlated with aggressive tumor behaviors and poor clinical outcomes in early‐stage lung adenocarcinoma after complete resection." (PMID 27456862, 2016). "In our study, MMP9 showed distinctive biological activity levels in different subtypes of lung adenocarcinoma." (PMID 27456862, 2016). "A high‐level MMP9 activity is correlated with aggressive tumor behaviors and poor clinical outcomes in early‐stage lung adenocarcinoma after complete resection." (PMID 27456862, 2016). "Here, a validated method was employed to determine the activity of MMP9 in human lung adenocarcinoma cells." (PMID 27456862, 2016). "A sensitive and validated method was employed for determining the activity of MMP9 in human lung adenocarcinoma cells in vitro." (PMID 27456862, 2016). "The objective of this study was to explore the prognostic value of matrix metalloproteinase 9 (MMP9) activity level in Chinese patients with stage I B lung adenocarcinoma." (PMID 27456862, 2016). "Our study demonstrated that tumor MMP-9 expression was a significant and independent prognostic factor for the relapse of lung adenocarcinoma." (PMID 25888323, 2015). "Higher expressions of MMP2 and MMP9 have also been correlated with poor prognosis in early stages of lung adenocarcinoma." (PMID 24811863, 2014). "CD147 overexpression upregulated the protein expression of MMP-9, and strengthened the proliferation and invasive ability of human lung adenocarcinoma cells." (PMID 23249715, 2012).
lung adenocarcinoma (continued). "This aim of this study is to construct a CD147 lentiviral expression vector, establish its stably transfected A549 cell line, and observe the effect of CD147 on MMP-9 proliferation as well as on the invasive ability of human lung adenocarcinoma cells." (PMID 23249715, 2012). "This led us to further speculate that GPX2 may enhance the invasive ability of lung adenocarcinoma A549 cells by controlling the expression of MMP2 and MMP9 proteins in lung adenocarcinoma cells." (PMID 35898928, 2022). "Of all human MMPs described so far, gelatinases (or type IV collagenases), i.e., MMP-2 (gelatinase-A) and MMP-9 (gelatinase-B), are recognized to be apparently correlated with pathological grading, staging, metastasis, and poor prognosis in patients with lung adenocarcinoma." (PMID 34204745, 2021). "MSCs enhance secretion of enzymatically active MMP9 in a panel of lung adenocarcinoma cells." (PMID 33119681, 2020). "Here we identified MMP9 as a target of MSC-induced priming in lung adenocarcinoma cells." (PMID 33119681, 2020). "A previous study demonstrated that EGCG could repress the activities of MMP-2 and MMP-9 in highly invasive CL1-5 lung adenocarcinoma cells." (PMID 32198390, 2020). "Forced LINC00461 expression decreased expression of miR‐195 and Bax, increased expression of HOXA10, MMP‐2, MMP‐9 and Bcl‐2, promoted cell proliferation, migration and invasion as well as tumour formation, and enhanced radiosensitivity of lung adenocarcinoma cells." (PMID 31967713, 2020). "The investigators suggested that the concentrations of MMP7 and MMP9 and the circulating tumor cell count could be used together as an effective, clinically predictive panel for lung adenocarcinoma metastasis and prognosis." (PMID 31191742, 2019). "The current study investigated the anti-proliferative, anti-motile and anti-invasive activities of an antagonist against CCR2, CAS 445479-97-0, by blocking the CCL2/CCR2 axis interaction and downregulating MMP-9 protein expression in human lung adenocarcinoma A549 cells in vitro." (PMID 28424406, 2017). "The relationship between MMP9 activity and clinical outcome of lung adenocarcinoma was significant." (PMID 27456862, 2016). "However, MMP9 activity measurement has great prognostic values for early‐stage lung adenocarcinoma patients." (PMID 27456862, 2016). "In the first comparison, proteins which most contributed to discriminate between 58 malignant (of which half were lung adenocarcinomas and half mesotheliomas) and their corresponding paired TB effusions were MMP-9, cathepsin-B, C-reactive protein, angiostatin, and chondroitin sulfate." (PMID 26962828, 2016). "Some reports have indicated that tumor MMP-9 expression is a prognostic factor for adenocarcinoma of the lung, and we analyzed that a higher proportion of the adenocarcinoma patients had positive tumor MMP-9 expression than squamous carcinoma in this study (28.0% vs. 61.5%; p = 0.001)." (PMID 25888323, 2015). "Moreover, in this study, Cox regression analysis revealed that tumor MMP-9 expression was an independent poor prognostic factor for the relapse of lung adenocarcinoma." (PMID 25888323, 2015). "In addition, MMP-9 expression was identified as an independent predictor of relapse of completely resected lung adenocarcinoma." (PMID 25888323, 2015). "The present study suggests that HPV infection may be involved in angiogenic promotion mediated by IL-8, MMP-2, MMP-9 up-regulation in lung adenocarcinoma." (PMID 23349885, 2013). "It is well documented that MMPs, in particular MMP-2 and MMP-9, which digest type-IV collagen and ECM, are strongly associated with the metastatic potential of many types of tumour cells, and their over-expression confers a worse prognosis in the early stage of lung adenocarcinoma." (PMID 34204745, 2021).
lung adenocarcinoma (continued). "Furthermore, miR-145 inhibited cell proliferation and promoted cell apoptosis through negatively regulating mTOR signaling pathway and decreasing MMP-2 and MMP-9 expression, the Bax/Bcl-2 ratio and the activity of the caspase-3 cascade in human lung adenocarcinoma A549 cells." (PMID 31582906, 2019). "Thus, this method could determine the MMP9 activity of fresh frozen specimens from five lung adenocarcinoma subtypes." (PMID 27456862, 2016). "Thus, more studies will be needed to confirm this, and furthermore, IHC staining to distinguish tumor MMP-9 expression may be useful to predict clinical outcomes after surgical resection of lung adenocarcinoma." (PMID 25888323, 2015). "In lung adenocarcinoma (LUAD), RGCC stimulates epithelial-mesenchymal transition (EMT), enhances cell migration and invasion, and reduces MMP-2 and MMP-9 protein activity and expression." (PMID 37576389, 2023). "Alpha-tomatine inactivates PI3K/Akt and ERK signaling pathways and nuclear factor (NF)-κB and AP-1 binding activities to inhibit the invasion and migration of human lung adenocarcinoma A549 cells by reducing u-PA MMP-2 and MMP-9." (PMID 31941156, 2020). "We found MMP-9 to be inhibited following knockdown of CSNK2β, which corroborates with the previous finding of MMP-9 inhibition with chemically inhibited CSNK2 in lung adenocarcinoma cells (Kim and Kim, 2013)." (PMID 33013272, 2020). "As expected, EGFR, ITGA2, KRAS, MMP9, NRAS and MAPK13 had higher levels in lung adenocarcinoma than in normal lung tissues." (PMID 32210363, 2020). "Subsequently, it is verified that 9 core targets for ginseng treatment of lung adenocarcinoma, namely, JUN, IL-1β, IL-2, ICAM1, HMOX1, MMP9, MMP2, PTGS2, and TNF, are closely related to the proliferation, migration, and apoptosis of lung adenocarcinoma cells." (PMID 32802118, 2020). "As we showed in our study, MMP1, MMP9 and MMP10 genes are elevated in human lung adenocarcinomas relative to normal tissue." (PMID 30988374, 2019). "In addition, factors previously identified to be specific markers of lung adenocarcinoma were upregulated, including PROM2, CLDN3, and TJP3, as were genes proposed to have potential diagnostic or prognostic value in human cancers, including MMP9, AGR2, SULF1, NHSL1, LGR5, MUC1, and PIK3C2G." (PMID 31434729, 2019). "The expression of TNF-α, IL-6, and macrophage marker CD68, as well as E-cadherin, vimentin, Twist, matrix metalloproteinase (MMP)-2, MMP-9, and SOD-2 were examined in AFG1-induced lung adenocarcinoma." (PMID 28801561, 2017). "A previous study shows that Gabra3 induced MMP-2 and MMP-9 expression through activating the JNK signaling pathway, which enhanced lymphatic metastasis in lung adenocarcinoma." (PMID 29078789, 2017). "Gelatin zymographs of conditioned media derived from human lung adenocarcinoma cell lines revealed two major bands of gelatinase activity at 68 and 92 kDa, which were characterized as matrix metalloproteinase (MMP)-2 and MMP-9 respectively." (PMID 10408691, 1999). "In addition, RGCC can induce EMT and enhance the migration and invasion of lung adenocarcinoma cells through increased MMP2 and MMP9 production and activity." (PMID 34015051, 2021). "Meanwhile, according to the results of qRT-PCR, it is speculated that ginseng can treat lung adenocarcinoma by up-regulated JUN, IL-1β, IL-2, ICAM1, HMOX1, MMP9, and MMP2 targets and down-regulated PTGS2 and TNF genes." (PMID 32802118, 2020). "We found that AFG1-induced lung adenocarcinoma expressed high levels of MMP-2 and MMP-9." (PMID 28801561, 2017).
lung adenocarcinoma (continued). "In addition, GABRA3 induced MMP-2 and MMP-9 expression through activation of the JNK/AP-1 signaling pathway, which enhanced lymphatic metastasis by lung adenocarcinoma both in vitro and in vivo." (PMID 27081042, 2016). "Thus, the significance of exploring the roles of MMP9 has been confirmed for tumor initiation and progression in some subtypes of IALSC/ATS/ERS lung adenocarcinoma." (PMID 27456862, 2016). "Moreover, previous studies included only limited analyses of tumor MMP-9 expression in early-stage adenocarcinoma, whereas this study evaluated stage I–IIIA operable adenocarcinoma of the lung." (PMID 25888323, 2015). "When AKR1B10 is silenced in lung adenocarcinoma cells, it suppresses their extravasation through the BBB in vitro, ex vivo microfluidic chip, and in vivo models; moreover, AKR1B10 silencing induced the downregulation of metastatic cells’ expression of matrix metalloproteinase MMP-2 and MMP-9." (PMID 39408656, 2024). "One study comparing different subgroups where high MMP-9 expression in tumor cells indicated worse outcome in resected lung adenocarcinomas, but not in lung squamous cell carcinomas, has been reported, thus further pointing to differences in biology between the subgroups." (PMID 29207598, 2017). "Moreover, inhibition of Matrix Metalloproteinase-9 (MMP-9) by lipocalin 2 (LCN2) can reduce almonertinib resistance, suggesting that the LCN2/MMP-9 axis might offer a potential strategy for addressing drug resistance in lung adenocarcinoma." (PMID 41291696, 2025). "However, studies have also found that ESR2 may be a new therapeutic target for lung adenocarcinoma in the future, as its downregulation reduces matrix metallopeptidase 2 (MMP-2) and MMP-9 expression, inhibiting the progression of lung adenocarcinoma through the MEK/ERK signaling pathway." (PMID 33868436, 2021).